FGF10 (fibroblast growth factor 10)
Diseases named in the same sentence as FGF10 in open-access papers (continued):
Sharing a sentence is not in itself a finding about the gene and the disease.
tumor (continued). "Furthermore, immunohistochemical location of FGF7 and FGF10 was investigated mainly in the stromal cells rather than the tumor cells." (PMID 24002438, 2013). "In addition, the removal of FGF10 from the culture medium did not reduce the growth of tumor organoids, suggesting that FGF signaling in these organoids might be predominantly autocrine." (PMID 39567475, 2024). "Next, we assessed the sensitivity of tumor organoids to FGFR inhibitor treatment when cultured with and without FGF10." (PMID 39567475, 2024). "To further ensure that the tumor organoids were mainly composed of tumor cells, we used a medium not containing the growth factors necessary for the culture of normal lung organoids, such as fibroblast growth factor 7 (FGF7), FGF10, R-spondin, and Noggin15,25,26." (PMID 33972544, 2021).
cancer (43 papers, 2008 to 2026). A tumor composed of atypical neoplastic, often pleomorphic cells that invade other tissues. "This leads to an overproduction of bioactive factors including FGF10, which in turns causes excessive epithelial development and possibly cancer development." (PMID 38600092, 2024). "Furthermore, FGF10 deregulation has been associated with human genetic disorders and certain forms of cancer." (PMID 30405705, 2018). "As a result, seven genes (FGF10, SERINE2, LSAMP, STXBP5, PDE5A, GLI2, FRMD6) were screened to develop the cancer associated fibroblasts (CAFs)-related risk signature (CAFRS)." (PMID 37280069, 2023). "In the context of cancer, aberrant signalling of FGF10 through FGFR2 IIIb, and to a lesser extent FGFR1 IIIb, has been implicated in a range of cancers." (PMID 37130917, 2023). "One study found subjects with dental agenesis had a major chance of family history of cancer and associations with AXIN2, FGF3, FGF10, and FGFR2 genes." (PMID 34378652, 2021). "FGF10 increased the migration of cancer cells in both normoxic and hypoxic conditions, and also changed the levels of EMT markers." (PMID 30837551, 2019). "Given this role of FGF10 in adult tissues, it is unsurprising that aberrant signaling of FGF10 through FGFR2b, and in some instances FGFR1b, contributes to the progression of a number of human cancers." (PMID 30405704, 2018). "Fibroblast Growth Factor 10-dependent responses range from cell proliferation, migration, and invasion, to multi-organ development, cancer or genetic disease progression." (PMID 30405705, 2018). "Here, we examine the mechanisms underlying FGF10-induced tumourigenesis and explore novel approaches to target FGF10 signaling in cancer." (PMID 30405704, 2018). "Expression of FGFR2 and FGFR1 are up-regulated in approximately 25% of pancreatic adenocarcinoma (PDAC) cases and elevated stromal FGF10 expression coupled with high cancer cell FGFR2b expression has been correlated with poor prognosis." (PMID 30405704, 2018). "Next, we examined the effects of adding growth factors HGF, FGF1, FGF7, and FGF10, to the culture medium of cancer cells." (PMID 25884729, 2015). "The important role of FGF-10 in type III EMT of cancer cells and the initiation of metastasis through various signaling pathways has also been suggested." (PMID 26060426, 2015). "As a consequence, the activated AMSCs can in turn produce FGF10 to induce CSC-traits of cancer cells." (PMID 26060426, 2015). "Overall, these results indicate that FGF10 stimulates migration and invasion of cancer cells through its specific receptor, FGFR2-IIIb." (PMID 18594526, 2008). "Fibroblast growth factor 10-positive stromal cells in cancer tissues were found in 42 cases (55.3%), and interestingly, were mainly localised close to cancer cells." (PMID 18594526, 2008). "Furthermore, FGF10 plays an important role in several significantly up-regulated signaling pathways, including the Pathways in cancer, Calcium signaling pathway, Regulation of actin cytoskeleton and PI3K-Akt signaling pathway." (PMID 35668376, 2022). "In particular, FGF7 and FGF10 are reported to signal from the stroma to the cancer cells." (PMID 33918004, 2021). "The 5p12 region harbors some important genes, for example GHR (growth hormone receptor), SEPPI, PAIP1, NNT and FGF10 that may be related to cancer (for complete list of genes in amplification regions)." (PMID 22363777, 2012). "Two, cancer cells may arise from a human equivalent of the Cd49f-positive mouse basal cell type under the influence of activated Akt, Fgf10, Erg1 and Ar." (PMID 21605402, 2011). "Next we examined which kind of cancer stromal cells expressed FGF10." (PMID 18594526, 2008). "Fgf10 gene mutations have been associated with diseases, such as aplasia of lacrimal and salivary glands (ALSG) and lacrimo-auriculo-dento-digital (LADD) syndrome; chronic obstructive pulmonary disease and certain cancer types, including breast, pancreatic, and gastric cancers." (PMID 30405705, 2018).
cancer (continued). "Together, these observations suggest that Wnt signaling pathway may play a unique role in activation of both VEGFC and FGF10 signaling, highlighting that an activation of Wnt signaling may be a potential common effect for AMSCs in response to Wnt-activated cancer cells in multiple settings." (PMID 26060426, 2015). "Since FGF-10 signalling provides a powerful regulatory signal, both in development and cancer, the aim of our present study was to identify a definitive transcription start site for Fgf-10 in order to investigate possible regulatory mechanisms that may control its expression." (PMID 19410332, 2009). "Moreover, of the 42 cancer tissue samples with FGF10-positive stromal cells, 29 (69.0%) showed high FGFR2 expression in cancer cells, and there was a significant correlation between the presence of FGF10-positive stromal cells and high FGFR2 expression in cancer cells (P=0.013)." (PMID 18594526, 2008). "Next, the expression profiles of CD44, FGF2, FGF10, KDM6A, FN1, and MMP2 were evaluated using the OcoDB database across different clinical stages, age groups, and racial categories in cancer patients." (PMID 39833941, 2025). "The MCODE analysis identified gene clusters for each cancer type with MYC, PCNA, PARP1, IDH1, FGF10, PTEN, and CCND1 as hub genes with high connectivity." (PMID 35001007, 2022). "Although not directly linked to cancer, BMP4 has been shown to prime FGFR to response to FGF2, FGF7 and FGF10 activation to increase proliferation in mammary epithelial cells." (PMID 34068954, 2021). "Indeed, the Wnt signaling of AMSCs was activated when they were co-cultured with cancer cells; sequentially the Wnt-activated AMSCs increased their expressions of EMT genes, including FGF10, VEGFC, MMPs, and cytokines." (PMID 26060426, 2015). "In the present study, we found that FGF10 was mainly responsible for the activation of AMSCs, which may in turn promotes the EMT of cancer cells to form the self-reinforcing loop." (PMID 26060426, 2015). "Together, these results indicate that FGF10 and VEGFC may be candidate paracrine factors responsible for the malignancy of cancer cells induced by Wnt-activated AMSCs." (PMID 26060426, 2015). "Of note, a robust induction of FGF10 and VEGFC by AMSCs may require cancer cells with abundant activation of canonical Wnt signaling." (PMID 26060426, 2015). "Indeed, extracellular signaling of FGF10, VEGFC, IL10 and TNFα of AMSCs was dramatically induced when they were co-cultured with cancer cells, and these molecules are suggested to have a direct or indirect impact on Wnt signaling pathway." (PMID 26060426, 2015). "These lung-specific functions of FGF10 may provide further insight into the molecular mechanisms by which FGF10, but not other FGFs with binding affinity for FGFR1b, affects cancer stem cells derived only from the lung." (PMID 31958320, 2020). "Interestingly, FGF10 induced expression of membrane type 1-matrix metalloproteinase (MT1-MMP) and transforming growth factor (TGF)-β1 mRNA in CFPAC-1 cells, and these genes may lead, at least in part, to cell migration and invasion of cancer cells." (PMID 18594526, 2008).
infection (6 papers, 2016 to 2024). The state of being infected such as from the introduction of a foreign agent such as serum, vaccine, antigenic substance or organism. "Indeed, we previously showed that FGFR kinase inhibitors suppress the infection of keratinocytes with herpes simplex virus I, while FGF7 or FGF10 had the opposite effect." (PMID 39340759, 2024). "The number of acetylated α-tubulin-positive ciliated cells was increased by culturing in medium without FGF10, which may explain the increased infection efficiency in medium without FGF10." (PMID 35637255, 2022).
Cardiovascular Diseases (3 papers, 2018 to 2025). "The recent findings revealing a crucial role for FGF10 in controlling both adult cardiomyocyte cell cycle reentry and stem cell differentiation and cell reprogramming toward the cardiogenic lineage provide potential therapeutic strategies for cardiovascular diseases." (PMID 30546382, 2018).
cerebral artery (3 papers, 2016 to 2025). "FGF-10 can prevent or reduce lung specific inflammation due to traumatic or infectious lung injury." (PMID 26869337, 2016). "FGF10 is known to protect neurons against oxygen-glucose deprivation injury in vitro, and FGF10 treatment depressed the triggered inflammatory factors of the TNF-α, IL-6, and nuclear factor-κB signaling pathways in a mouse middle cerebral artery occlusion model." (PMID 34383782, 2021).
metabolic disease (3 papers, 2014 to 2022). A congenital disorder (due to inherited enzyme abnormality) or acquired (due to failure of a metabolically important organ) disorder resulting from an abnormal metabolic process. "In addition, FGF1, FGF10, and FGF21 have been shown to be adipokines with crucial roles in WAT or BAT functions, suggesting new roles for FGFs and potential therapeutic strategies for metabolic disorders." (PMID 24605108, 2014).
adenocarcinoma (2 papers, 2018 to 2022). A common cancer characterized by the presence of malignant glandular cells. "Xenografts derived from FRS2α(wt) prostate cells mixed with FGF10-UGSM showed adenocarcinoma, whilst xenografts of FRS2α(G2A) cells with FGF10-UGSM cells showed normal prostate tubules." (PMID 30405704, 2018). "In vivo models have shown that elevated paracrine FGF10 stimulation of mouse prostate epithelial cells led to the development of adenocarcinoma, predominantly via activation of epithelial FGFR1." (PMID 30405704, 2018). "In a model of FGF10-induced prostate tumourigenesis, enhanced phosphorylation of Src-family kinases (SFKs) was detected in the adenocarcinoma lesions." (PMID 30405704, 2018).
genetic diseases (2 papers, 2018 to 2023). "Finally, current gaps in our understanding of FGF10 functions, such as the relative contribution of receptor isoforms to signaling activation, will be discussed in the context of genetic disorders and tumorigenesis." (PMID 30405705, 2018).
respiratory disease (2 papers, 2021). "More on these findings will be further discussed in the FGF10 and respiratory disease section." (PMID 34124037, 2021).
inflammation (1 paper, 2019). Aberrant reaction of the microcirculation characterized by movement of fluid and leukocytes from the blood into extravascular tissues. "KGF-2, also known as fibroblast growth factor-10 (FGF-10), shares homology with KGF and plays an important role in lung development, lung inflammation, and repair." (PMID 31379970, 2019).
psychiatric disorder (1 paper, 2017). A disorder characterized by behavioral and/or psychological abnormalities, often accompanied by physical symptoms. "Ten genes were enrichedwith several KEGG pathways, and ROBO2, CXCL2, EPHA5,EPHA6, ANGPT2, FGF10, GHF genes was found to be enrichedwith pathways influencing psychiatric disorders like Axonguidance, RAP1 Signaling pathways, RAS Signaling pathwaysetc." (PMID 28539732, 2017).
FGF10 also shares sentences with these, for which no sentence is quoted: acute lung injury (4 papers); aplasia of lacrimal and salivary glands (3); cystic fibrosis (3); fibrosis (3); corneal diseases (2); COVID-19 (2); cryptorchidism (2); Micropenis (2); prostate tumor (2); rotator cuff tears (2); acute kidney injury (1); alveolar capillary dysplasia (1); Alzheimer disease (1); anal atresia (1); autosomal recessive mental retardation type 13 (1); Barrett’s metaplasia (1); bile duct diseases (1); cholangiocarcinoma (1); choroidal neovascularization (1); chronic lung disease (1); cloacal exstrophy (1); colitis (1); colonic atresia (1); Compton-North congenital myopathy (1); congenital hypothyroidism (1); congenital malformation (1); cytomegalovirus infection (1); depression (1); diabetes (1); Duchenne muscular dystrophy (1).
A further 26 diseases each share a sentence with FGF10 in 1 paper.